HSFX3 (heat shock transcription factor family, X-linked member 3)
Gene: Protein-coding gene on chromosome X (149,548,210 to 149,549,924, reverse strand). Ensembl gene ENSG00000283697.
Subcellular location: Nucleus
Gene Ontology:
Molecular function: DNA-binding transcription factor activity, RNA polymerase II-specific; RNA polymerase II cis-regulatory region sequence-specific DNA binding; DNA-binding transcription factor activity; sequence-specific DNA binding
Biological process: regulation of transcription by RNA polymerase II; regulation of DNA-templated transcription
Cellular component: chromatin; cytosol; nucleus
Homologues: Orthologues: macaque HSFX3 (87% identical), Caenorhabditis elegans hsf-1 (14% identical), Drosophila melanogaster Hsf (14% identical). Paralogues in human: HSFX4 (99% identical), HSFY1 (23% identical), HSFY2 (23% identical), HSFX1 (19% identical), HSFX2 (19% identical), HSF1 (17% identical), HSF5 (17% identical), HSF4 (16% identical), HSF2 (14% identical).